CYP1A1 (cytochrome P450 family 1 subfamily A member 1)
Diseases named in the same sentence as CYP1A1 in open-access papers (continued):
Sharing a sentence is not in itself a finding about the gene and the disease.
breast carcinoma (continued). "In verifying the results of the transcriptomic experiment, THC-treated breast cancer cells were detected by WB assay, and CYP1A1, PD-L1, and NF-κB signaling pathway-related proteins were detected." (PMID 36707875, 2023). "The results showed that THC inhibited the expression of CYP1A1, NF-κB, P-IκBα, and PD-L1 in breast cancer cells." (PMID 36707875, 2023). "Al-Dhfyan and colleagues demonstrated that the activation of AhR/CYP1A1 in breast cancer MCF-7 cells by TCDD or 7,12-dimethylbenz[a]anthracene induces the overexpression of β-catenin and its downstream target cyclin D1 at mRNA and protein levels." (PMID 37232717, 2023). "The “wound recovery” and invasion ability of breast cancer cells in the CYP1A1 group were enhanced, whereas the metastasis and invasion ability of cells in the THC + CYP1A1 group were enhanced compared with that in the THC group." (PMID 36707875, 2023). "Another group also reported the development of CYP1A1-targeting prodrugs of anti-mitotics, which exert potent cytotoxicity in both in vitro and in vivo models of breast cancer." (PMID 38001897, 2023). "An earlier paper about breast cancer MCF-7 cells showed that the activation of AhR/CYP1A1 promotes chemoresistance through the triggering of Wnt/β-catenin and ALDH pathways, which mediate the development, maintenance, and self-renewal of CSCs." (PMID 37232717, 2023). "A previous study in breast cancer MCF-7 cells showed that activation of AhR/CYP1A1 increased the chemoresistance by activating the Wnt/β-catenin and ALDH pathways, pathways that mediate CSCs development, maintenance, and self-renewal." (PMID 35742838, 2022). "Breast cancer can be prevented by eating foods that change the activity of certain cytochrome P450 enzymes, including CYP1A1, CYP1A2, CYP1B1, CYP2B6, CYP3A4, CYP19A1, and CYP24A1." (PMID 36571647, 2022). "It has been published that via preventing PTEN and stimulating β-Catenin and Akt pathways, the AhR/CYP1A1 signaling pathway affected the phenotypes of breast cancer stem cells, such as growth, development, renewal, and chemoresistance." (PMID 36685893, 2022). "A similar relationship between CYP1A1 and SULT1A1 activity and reduced breast cancer risk has been demonstrated previously." (PMID 36203093, 2022). "Gene knockdown studies in breast cancer cells identified the role of CYP2S1 in metabolically inactivating benzothiazoles while induction of CYP1A1 remained crucial for their activation and anti-tumour properties." (PMID 33809117, 2021). "Another study in an MCF-7 breast cancer cell line supported RelA involvement in repressing CYP1A1 expression upon treatment with the proinflammatory cytokine IL-1β." (PMID 33451129, 2021). "In Taiwanese women it was observed that of the three gens, i.e., CYP17, CYP1A1, and COMT, low activity of the COMT genotype was associated with the highest relative risk of breast cancer (RR = 4.0; 95% CI 1.12–19.8)." (PMID 34462889, 2021). "Knockdown of CYP1A1 has been shown to impair proliferation and survival in the breast cancer cell lines MCF-7 and MDA-MB-231 through activation of AMPK signaling and inhibition of the phosphorylation of AKT, ERK and P70S6K." (PMID 33809117, 2021). "The PAIB-SOs have been shown to display potent cytotoxic activity in both CYP1A1-expressing hormone-dependent and chemo-resistant breast cancers cells both in vitro and in vivo via N-dealkylation and prodrug activation." (PMID 33809117, 2021). "Increased basal level expression of CYP1A1 has also been observed in spheroids cultured from MCF-7 breast cancer cells, compared to the monolayer, which was suppressed upon co-culture with CD14+ cells in a macrophage-shaped environment." (PMID 33809117, 2021). "There is also some evidence that CYP1A1 is important for maintaining the integrity of breast cancer stem cells (BCSCs), possibly by acting through β-catenin and PTEN/AKT signaling." (PMID 33809117, 2021).
breast carcinoma (continued). "In this study, univariate logistic regression analysis showed that CYP1A1, CYP1B1, and SULT1A1 gene polymorphisms are closely related to the occurrence of breast cancer." (PMID 33632172, 2021). "Elevated CYP1A1 mRNA expression has been detected to varying degrees in many breast cancer subtypes which supports its potential as a drug target in breast cancer treatment." (PMID 33809117, 2021). "It has also been proved to block the cell cycle of CYP1A1 (Cytochrome P450 Family 1 Subfamily A Member 1)-overexpressing MCF-7 breast cancer cells." (PMID 34203624, 2021). "Carnosol treatment (40 μM) for 8 h was shown to have a similar effect on breast cancer cells as CYP1A1 knockdown via siRNA." (PMID 33049974, 2020). "Rodriguez and Potter (2013) used small interfering RNA (siRNA) in MCF7 and MDA-MB-231 breast cancer cells to knockdown CYP1A1 in order to investigate the role of this enzyme in breast cancer progression." (PMID 33049974, 2020). "In an earlier study, the presence of homozygous high-risk alleles in three genes, i.e., CYP17, CYP1A1, COMT, have been shown to influence the development of breast cancer." (PMID 31980012, 2020). "Eupatorin inhibits CYP1A2 and the in vitro proliferation of MDA-MB-468 human breast cancer cells that express CYP1A1." (PMID 32425779, 2020). "The AhR/CYP1A1 pathway participates in carcinogenesis by mediating stem properties, the formation of mammospheres, expansion of breast cancer stem cells, and the transcriptional activity of AhR is mainly implicated in such effects." (PMID 32670863, 2020). "Cytochrome P450-1A1 (CYP1A1) promotes breast cancer proliferation and survival through the suppression of AMPK signaling." (PMID 32326308, 2020). "Summing up, luteolin and apigenin inhibited pro-intravasative mechanisms in MDA-MB231 breast cancer cells at the levels of CYP1A1 activity and MMP1 expression." (PMID 29593542, 2018). "CYP1A1 inhibition by siRNA and proadifen in breast cancer cells or by proadifen in CRC cells reduced the synthesis of 12(S)-HETE and the formation of CCIDs in EC monolayers as well and thus, further supports a role of 12(S)-HETE in the malignancy of CRC." (PMID 28013338, 2017). "TCDD has been shown to inhibit estradiol-induced cell growth and proliferation as well as other pathways regulated by estrogens, including methylation of CYP1A1, in a variety of human breast cancer cell culture lines." (PMID 28865460, 2017). "Differently, in breast cancer, CYP1A1 regulates proliferation and survival of tumor cells, while CYP1B1 indirectly causes the generation of free radicals." (PMID 29657291, 2017). "In our previous study, TCDD did induce both aromatase and CYP1A1 via binding to AhR in breast carcinoma cell lines." (PMID 29039776, 2017). "E2 and the resulting hydroxylated metabolites from cytochrome P450s CYP1A1 and CYP1B1 have been implicated in breast cancer." (PMID 28212313, 2017). "In that, it has been previously reported that TCDD, AhR ligand and potent CYP1A1 inducer, increased human breast cancer MCF-7 cell proliferation and the number and size of the mammospheres (CSC populations) via the suppression of apoptosis." (PMID 28103884, 2017). "Genes such as NAT1, NAT2, CYP1A1, COMT, BRCA1, BRCA2 or DNA repair genes have been reported to alter the relationship between smoking and breast cancer risk." (PMID 27754415, 2016). "Supporting our suggestion, Rodriguez and Potter found that CYP1A1 induction promotes breast cancer proliferation and progression." (PMID 27800121, 2016). "On the other hand, of the polymorphisms investigated comparing breast cancer smokers and healthy smokers, statistically significant associations between two genetic variants and risk of breast cancer in smokers were observed (XRCC3 Met241, CYP1A1 Ile462)." (PMID 27754415, 2016).
breast carcinoma (continued). "Many studies have evaluated the association between SNPs in estrogen-related genes, such as CYP17, CYP19, CYP1A1, CYP1B1, COMT, GSTP1, and ERα/β, and the risk of breast cancer, especially in postmenopausal women." (PMID 25689428, 2015). "Conversely, we found that Cyp1a1 was reduced in adjacent mammary gland and mammary tumors of DMBA-treated animals." (PMID 26715507, 2015). "CYP1A1 expression was first measured in MCF7 breast cancer cells that were grown in estrogen-free medium for three days and then treated with either 10 nM TCDD or 50 μM DIM, alone, or in combination with 100 nM E2 for 24 h." (PMID 25048790, 2014). "Fourthly, in breast cancer cells, TCDD induces the expression of CYP1A1 and CYP1B1, which encode enzymes that convert E2 into catecholestrogens." (PMID 25257533, 2014). "Our laboratory has focused efforts to unravel the mechanism(s) involved in the CYP1A1 gene repression by ERα in breast cancer cell lines." (PMID 25257533, 2014). "Down-regulation of CYP1A1 has also been shown in cells of the respiratory tract, breast cancer cells and hepatocytes exposed to SCNTs." (PMID 25102311, 2014). "Although constitutive expression of SULT1A1 has been associated with cancer cell sensitivity to AF, AhR’s responsiveness to AF, as indicated by induction of CYP1A1, appears to be essential for the antiproliferative activity of AF in breast cancer cell lines." (PMID 24058584, 2013). "Expression of estrogen receptor α (ERα) and AhR-mediated transcriptional induction of CYP1A1 can sensitize breast cancer cells to AF." (PMID 24058584, 2013). "Several phytochemicals including the flavonoids quercetin was reported to induce the expression of Cyp1A1 in MCF-7 breast cancer cells." (PMID 23894592, 2013). "Supporting the activity of tranilast as an AHR agonist we find that: 1) It strongly induces CYP1A1 expression (a classic marker of AHR activity) in breast cancer cells." (PMID 21072210, 2010). "Although tranilast has a much lower affinity for the AHR than 3-MC, it can induce comparable expression of CYP1A1 in breast cancer cells when added to cultures at pharmacological concentrations (≥100 μM)." (PMID 21072210, 2010). "These agonists are strong inducers of the CYP1A1 enzyme, and we found that tranilast increases CYP1A1 expression in breast cancer cells by EROD enzymatic assay in vitro." (PMID 21072210, 2010). "CYP1A1 and CYP1A2 genotypes are associated with the generation of catecholestrogens, which have been associated with breast cancer risk." (PMID 19287484, 2009). "Eupatorin strongly inhibits the in vitro proliferation of MDA-MB-468 human breast cancer cells that express CYP1A1, but it is inactive in normal breast MCF-10A cells, devoid of any CYP1A1 activity." (PMID 19531241, 2009). "Several studies highlighted the role of XME gene polymorphisms such as CYP1A1, CYP1B1, CYP2D6, mEH, GSTT1, GSTM1 and NAT1 in treatment efficacy as well as survival after treatment of breast carcinoma." (PMID 18423013, 2008). "CYP1A1 has been involved in the activation of two main chemotherapeutic agents in breast cancer cell lines." (PMID 18454852, 2008). "Regardless of the difference in activity, our study reinforces the pivotal role of CYP1 enzymes and mainly CYP1A1 in breast cancer prevention and therapy through the activation of xenobiotics." (PMID 18454852, 2008). "A cohort study was conducted to examine the role of genetic polymorphisms in three estrogen metabolizing enzymes (COMT, CYP1A1, CYP1B1) and the two estrogen receptors (ESR1, ESR2) in the progression of benign breast disease (BBD) to breast cancer." (PMID 16808847, 2006). "The aim of the present study was to analyze the associations between genetic polymorphisms in three estrogen metabolizing enzymes (COMT, CYP1A1, CYP1B1) and the two estrogen receptors (ESR1, ESR2) and the risk of developing breast cancer among women with BBD." (PMID 16808847, 2006).
breast carcinoma (continued). "Genotype frequencies for CYP1A1, and ORs for breast cancer, have previously been reported for the CBCS." (PMID 15642161, 2005). "Our results confirm previous reports that CYP1A1 M2-containing genotypes modify the association between PCB exposure and risk of breast cancer." (PMID 15642161, 2005). "ORs for breast cancer per 0.10 ng/ml increase in lipid-adjusted total PCBs showed only slight differences according to CYP1A1 M2 genotypes in white women." (PMID 15642161, 2005). "Moysich and colleagues reported that breast cancer risk was significantly increased among women with elevated PCB body burden and CYP1A1 M2 genotypes who had ever smoked cigarettes." (PMID 15642161, 2005). "Notably, FOXA1 and RAB25 are strongly implicated in breast cancer biology, and FOXA1 has been directly linked to the aryl hydrocarbon receptor (AHR), the main regulator of CYP1A1." (PMID 41901204, 2026). "There are some genetic association studies conducted on Bangladeshi Breast cancer and cervical cancer population to evaluate susceptible single nucleotide polymorphisms of INSIG2, HLA-DRB1, GCNT1P5, IL1β, IL4R, IL6, FGFR2, CYP1A1, ESR1 genes and disease outcome." (PMID 40920780, 2025). "Additionally, CYP1A1, a key Phase I DME, has previously been linked to increased breast cancer risk, while high CYP26B1 has been associated with poor prognosis in colorectal cancer." (PMID 39997761, 2025). "In the case of breast cancer cells, the CYP1A1 protein level was slightly reduced by 3,4,2′-trimethoxy (3MS) and 3,4,2′,4′-tetramethoxy (4MS), and the CYP1B1 expression was decreased as a result of the treatment with 4MS, but only at the transcript level in MDA-MB-231 cells." (PMID 40807256, 2025). "On the other hand, nobiletin and polymethoxyflavone were shown to induce their own metabolism, which may affect their cytostatic effect in MCF7 breast cancer cells, via CYP1A1 and CYP1B1 upregulation." (PMID 40807256, 2025). "According to these predictions, the mechanism of SA in breast cancer may involve the regulation of several proteins, including cytochrome enzymes (CYP1A1 and CYP3A4), PRKCA, CASP8, SIRT1, and CTNNB1." (PMID 40427522, 2025). "Moreover, CYP1A1 was found to play a critical role in breast cancer stem cell integrity, whereby it controlled cell growth, self-renewal, and chemoresistance, presumably via catenin and PTEN/AKT signaling." (PMID 38001897, 2023). "In clone formation experiment, the formation speed and size of breast cancer cell clones in the CYP1A1 group increased compared with the control group, whereas the formation ability of breast cancer cell clones in the THC + CYP1A1 group decreased compared with the THC group." (PMID 36707875, 2023). "Collectively, these results showed that TH could effectively trigger apoptosis and inhibit the migration of breast cancer cells via the CYP1A1/NF-κB signaling pathway, indicating that THC serves as a potential candidate drug for the treatment of breast cancer." (PMID 36707875, 2023). "After CYP1A1 knockdown, the apoptosis rate of breast cancer cells in the sh-CYP1A1 group increased." (PMID 36707875, 2023). "This is in consistent with previous studies which reported that tamoxifen could upregulate CYP1A1 expression in MCF7 breast cancer cells in an ER-independent manner." (PMID 35642027, 2022). "For instance, quercetin was shown to be an agonist of CYP1A1 in breast cancer cells." (PMID 36118099, 2022). "In addition to mutagenicity, multiple flavonoids can potentiate their cytotoxicity toward breast cancer cells after CYP1A1 and CYP1B1 mediated metabolic activation." (PMID 34744736, 2021). "Taxifolin suppressed breast cancer by regulating the AhR and Cytochrome P450 CYP1A1 pathway." (PMID 34113483, 2021). "The complex mechanism of action between AhR/CYP1A1 and breast cancer still requires further study." (PMID 33542691, 2020).
breast carcinoma (continued). "Overall, emodin may exhibit anti-tumor activity by activating the AhR/CYP1A1 pathway, which lays the foundation for the application of emodin in breast cancer treatment." (PMID 33542691, 2020). "Furthermore, as a steroid-metabolizing enzyme, CYP1A1 is part of cancer metabolic processes relevant to steroid hormone responsive tumors, such as breast cancer, ovarian cancer, and prostate cancer." (PMID 32730293, 2020). "The CYP1A1 gene is thought to be involved in breast cancer because of its role in the metabolism of the polycyclic aromatic hydrocarbons and in the oxidative metabolism of estrogens that might increase the risk of oxidative stress and cancer." (PMID 29707532, 2018). "CYP1A1 is particularly implicated in lung, colorectal, breast, and prostate cancers, CYP1B1 in hormone dependent cancers of the prostate, breast, and endometrium, and CYP1A2 in colorectal, lung, and breast cancers." (PMID 29462868, 2018). "In addition, recent studies from our laboratory and others have demonstrated the pivotal role of AhR/CYP1A1 in development of breast cancer." (PMID 28103884, 2017). "Expressional variation of CYP1A1 has shown down-regulation of CYP1A1 in breast cancer." (PMID 27754415, 2016). "Most previous studies of CYP1A1 polymorphisms and breast cancer divided smokers into ever or never groups, and did not analyse the effects of intensity, years of smoking or age at initiation." (PMID 27754415, 2016). "Furthermore, some variants in estrogen-related genes, such as CYP1A1 T3801C, CYP1A1 A2455G, and COMT Val158Met, were identified as susceptibility loci in breast cancer development according to recent meta-analysis reports." (PMID 25689428, 2015). "Basal Cyp1a1 was reduced by 30 and 70 % respectively in adjacent mammary gland and mammary tumors." (PMID 26715507, 2015). "Here, we focus on recent advances in the understanding of molecular mechanisms that mediate this crosstalk repression, and particularly on how ERα represses the AhR target gene CYP1A1, and could subsequently promote breast cancer." (PMID 25257533, 2014). "However, negligible relations between polymorphic CYP1A1 MspI and gastric cancer, colorectal cancer, breast cancer and esophageal cancer risks have been found." (PMID 22846179, 2012). "Several recent meta-analyses have reported that there is no over-all association with breast cancer risk for most of the common CYP1A1 polymorphisms." (PMID 22754477, 2012). "Phortress, which entered early Phase I clinical trials in 2004, induces CYP1A1 in breast cancer sensitive cell lines, such as MCF-7, T-47D and IGROV (IC50 < 10 nM) and is further metabolized by CYP1A1 to reactive electrophillic species which results in DNA adduct formation." (PMID 19531241, 2009). "Thus, the breast carcinoma cell line MDA-MB-468 constitutively expresses CYP1A1 and, after induction, increases CYP1A1 levels and expresses low levels of CYP1B1." (PMID 18454852, 2008). "However, low levels of CYP1B1 and CYP1A1 activity have been reported for similar breast cancer cell lines such as MDA-MB-436, MDA-MB-231, MDA-MB-157, and T47 in the absence of TCDD, whereas in its presence the activity was largely augmented." (PMID 18454852, 2008). "However, biologic evidence and previous epidemiologic studies support the possibility of causal interaction between CYP1A1 genotypes (in particular, M2-containing genotypes) and PCB exposure in the etiology of breast cancer." (PMID 15642161, 2005). "Data from the CBCS provides evidence that subgroups of women with CYP1A1 M2 and M3 polymorphisms and high levels of PCB exposure might have a modestly elevated risk of breast cancer." (PMID 15642161, 2005). "In addition, meta-analyses combining individual-level data from epidemiologic studies of CYP1A1 and breast cancer will be needed to generate more precise estimates of the joint effects of PCBs and CYP1A1 genotypes." (PMID 15642161, 2005).